TFF3 (trefoil factor 3)
Diseases named in the same sentence as TFF3 in open-access papers (continued):
Sharing a sentence is not in itself a finding about the gene and the disease.
cancer (105 papers, 2004 to 2026). A tumor composed of atypical neoplastic, often pleomorphic cells that invade other tissues. "Previous studies have suggested that TFF3 is closely associated with cancer migration in various cancers, although less research has focused on its role in LNM." (PMID 41551914, 2026). "Recent findings have suggested that the biological role of TFF3 extends beyond mucosal protection, and is also associated with oncogenic progression in different types of cancer." (PMID 39920140, 2025). "Interacting networks revealed a significant association between FGFBP and trefoil factor 3 (TFF3), a novel prognostic marker in various cancers, at transcriptional and translational levels." (PMID 35626334, 2022). "Further guidance will be required to tailor the follow-up of patients diagnosed via the Cytosponge-TFF3 procedure, depending on their degree of risk of progressing to dysplasia or cancer according to the clinical surveillance guidelines." (PMID 32738955, 2020). "This indicates that TFF3 expression is associated with resistance to chemotherapy as it is highly expressed in residual carcinoma." (PMID 30744593, 2019). "Nonetheless, studies on the diagnostic potential of serum TFF3 have gradually concentrated on its clinical use in the diagnosis and treatment of malignant tumors." (PMID 24282531, 2013). "Our findings reveal that SPINK1 expression was predominantly observed in a subgroup of cancers that expressed TFF3 (n = 6/6, p-value 0.013 highlighting the potential significance of assessing both TFF3 and SPINK1 statuses in order to stratify the risk of PCa patients." (PMID 38256434, 2024). "Furthermore, the number of TFF3-positive tiles allowed us to predict with high accuracy patients harbouring clinically relevant BO from focal IM pathologies that likely have a low cancer risk." (PMID 35843173, 2022). "For example, Tff3, Hpse, Slit1, Spon1, Spock1, and Spock3 are associated with increased cancer cell invasion and were upregulated in Rreb1-/-, and Selenbp1 and Serpin6b are tumor suppressor genes that were downregulated." (PMID 33929320, 2021). "Because the detection of early-stage cancer is associated with improved survival, our hypothesis is that the combination of TFF3 with pepsinogen could enhance the sensitivity of EGC detection." (PMID 29977284, 2018). "Thus, the TFF3 promoter was frequently hypomethylated in PC and loss of TFF3 promoter methylation was highly cancer-specific in this RP cohort, indicating promising diagnostic potential." (PMID 28930171, 2017). "Automated Cytosponge-TFF3 gland quantification may enable thresholds to be set to trigger confirmatory gastroscopy to minimize overdiagnosis of focal IM pathologies with very low cancer-associated risk." (PMID 35843173, 2022). "However, patients who are TFF3 positive may have focal IM pathologies with very low cancer risk and gastroscopy could be obviated." (PMID 35843173, 2022). "Furthermore, TFF3 is associated with the transformation, growth, and migration of cancer cells." (PMID 25222179, 2014). "Analysis of the pan-cancer scRNA-seq dataset deciphered that TFF3 was predominantly expressed in malignant epithelial cells." (PMID 41551914, 2026). "We found that TFF3 was more highly expressed in cancer cells than in normal breast epithelial cells." (PMID 41551914, 2026). "Integration of Mendelian colocalization signatures with pan-cancer spatial atlases established the TFF3 oncogene as a regulator of spatial EMT programs." (PMID 41551914, 2026). "We validated malignant-cell-specific TFF3 expression across pan-cancer single-cell profiles and in PBC lineages." (PMID 41551914, 2026). "In a pan-cancer scRNA-seq cohort, TFF3 was predominantly expressed in malignant epithelial cells, with its peak expression observed in BRCA cell lines." (PMID 41551914, 2026). "AMPC leads to the rapid degradation of the monomeric form of TFF3, thereby diminishing TFF3-mediated signaling pathways crucial for cancer cell survival." (PMID 39920140, 2025).
cancer (continued). "The inclusion of genes like AK5, CDC20, and TFF3, which have established roles in cancer cell proliferation and metastasis, underscores their importance in a predictive model." (PMID 40161494, 2025). "Intriguingly, the high-throughput anti-cancer compound screening assays demonstrated that TFF3 inhibition by AMPC synergized most effectively with compounds targeting four distinct RTKs, EGFR, VEGFR, c-KIT, and c-MET in MDA-MB-361 and BT474 cells." (PMID 39920140, 2025). "Previous studies have shown that upregulation of TFF1 and TFF3 in cancer cells can facilitate EMT and confer resistance to chemotherapy and radiotherapy." (PMID 38709264, 2024). "Clinical and experimental findings indicate that TFF3 is also involved in many pathological processes, including mucosal disorders and cancer." (PMID 37569301, 2023). "Increased TFF3 expression exerts pleiotropic effects that alter multiple biological processes involved in cancer development and progression." (PMID 35332126, 2022). "One of these genes/proteins, the trefoil factor 3 (TFF3), was part of the original set of ‘seed’ cancer markers used." (PMID 36140706, 2022). "STAT3 inhibition has been consistently shown to hinder the proliferation, invasion, and survival of TFF3-induced cancer cells." (PMID 35039476, 2022). "It has been demonstrated that TFF3 promotes cancer cell survival, proliferation, invasion, migration, angiogenesis, metastasis, and drug resistance." (PMID 35332126, 2022). "A high expression level of TFF3 was observed in 59.1% (39/66) of cancer tissue, whereas in normal tissue, high expression was observed in 24.1% (13/54) of samples." (PMID 35332126, 2022). "Increasing evidence has indicated that TFF3 exerts crucial roles in the development and progression of various human cancers." (PMID 35332126, 2022). "Tff3 facilitates migration and inhibits apoptosis, and its expression is increased in a variety of cancers." (PMID 34068249, 2021). "TFF3 expression in the epithelial cells of the cancer tissues was significantly increased compared to that in the adjacent normal mucosa." (PMID 34262017, 2021). "TFF3 expression is increased in a number of cancers, including breast, liver, prostate, gastric, and endometrial as compared with the respective noncancerous tissues." (PMID 31685806, 2019). "A potential correlation between doxorubicin sensitivity and TFF3 expression in a panel of ER + MC cell lines was determined using the Genomics of Drug Sensitivity in Cancer Project and Cancer Cell Line Encyclopedia (CCLE)." (PMID 31658702, 2019). "Aberrant expression of TFF3 has been reported in various cancers including those of the breast, endometrium, prostate, cervical, liver, colon, gastric and lung." (PMID 31658702, 2019). "As TFF3 exhibits increased expression in various cancers to promote cancer progression, therapeutic resistance, and relapse, and is associated with poor patient survival, it is a potential actionable target in cancer." (PMID 31685806, 2019). "We have also shown significant reduction in proliferative and apoptotic activities in cancer cells of residual tumors in conjunction with high expression of TFF3 in the majority of residual tumors." (PMID 30744593, 2019). "For example, the increased expression of trefoil factor family 3 (TFF3) is identified in a variety of cancers." (PMID 31258820, 2019). "As aldehyde dehydrogenase-1 (ALDH1) is known as a cancer stem cell marker the effect of TFF3 on modulating the ALDH1-positive cell population was examined." (PMID 31835445, 2019). "TFF3 has been reported to be involved in the regulation of cancer stem cell (CSC)-like behavior in cancer." (PMID 31685806, 2019). "We have also observed that several cancer stem cell related genes were regulated by forced expression of TFF3 in H1299 cells or by AMPC treatment of H1299 cells." (PMID 31685806, 2019).
cancer (continued). "TFF3 protein expression was examined by immunohistochemistry (IHC) using a tissue microarray (TMA) containing 108 cancer tissues and 106 matched normal prostate tissues." (PMID 30139961, 2018). "It is entirely plausible that a proportion of cancers that are intially dependent on TFF3 stimulation of oncogenic transformation for their establishment will later lose dependence on TFF3 for their progression." (PMID 30451834, 2018). "This is exemplified in histopathological studies of TFF3 expression where between 608 and 83%6 of carcinoma are TFF3 positive." (PMID 30451834, 2018). "To validate the cancer-specific hypomethylation of TFF3 in an independent RP patient cohort, we analyzed 450K data from TCGA for 497 PC and 50 AN tissue samples." (PMID 28930171, 2017). "TFF3-mediated activation of STAT3 has also been previously reported to stimulate progression of different cancers." (PMID 29100386, 2017). "In cancer cells, TFF3 promotes cell migration, invasion and metastasis by reducing cell–cell and cell–matrix interactions and enhancing cell scattering in bronchiole or other epithelia cells." (PMID 28070169, 2017). "In the same study, we showed that TFF3 promoter methylation and RNA expression levels were inversely correlated in a small set of prostate (cancer) cell lines, suggesting epigenetic regulation of gene activity." (PMID 28930171, 2017). "The increased doxorubicin efflux and enhanced cancer stem cell-like behavior of the doxorubicin-resistant Hep3B cells was observed to be dependent on TFF3 expression." (PMID 28445151, 2017). "In summary, we here report significant cancer-specific hypomethylation of the TFF3 promoter region in two independent patient cohorts, including a total of 787 PC and 155 NM prostate tissue samples." (PMID 28930171, 2017). "Up-regulation of TFF3 in cancer cells was accompanied by activation of multiple pathways including PI3K, MAPK and JAK/STAT pathways which were associated with cellular proliferation, apoptosis, migration, invasion and clonogenic survival." (PMID 28070169, 2017). "The overexpression of TFF3 has also been reported clinically in breast, prostate, lung, gastric and liver cancers." (PMID 29100386, 2017). "First, using quantitative methylation specific PCR (qMSP) analysis, we found highly frequent and cancer-specific TFF3 promoter hypomethylation in a set of 292 PC compared to 33 non-malignant (NM) prostate tissue samples." (PMID 28930171, 2017). "For practical use of serum TFF1, TFF2, and TFF3 for cancer screening, subjects who were detected to have high serum TFF3, should be scrutinized by imaging examination." (PMID 28687783, 2017). "In contrast, depletion of TFF3 increased doxorubicin sensitivity and decreased cancer stem cell-like behavior of Hep3B cells." (PMID 28445151, 2017). "TFF3 has previously been demonstrated to stimulate the oncogenic behaviour of various carcinoma cells." (PMID 29100386, 2017). "TFF3 overexpression is frequently observed in human cancers and thus, was thought to induce cancer growth." (PMID 27626280, 2016). "Three closely related trefoil factors (TFFs) known in humans, pS2 (TFF1), spasmolytic polypeptide (SP or TFF2) and intestinal TFF (ITF or TFF3), have been previously reported to be associated with the development of various types of cancer." (PMID 24765170, 2014). "Higher serum levels of TFF3 were significantly correlated with distant metastasis and an advanced stage in the two types of cancer (P < 0.05)." (PMID 25031551, 2014). "Our results suggested that urine TFF3 is a different indicator to serum levels and that multiple factors can affect urine TFF3 levels, such as the secretion of cancer, tubular secretion and the GFR." (PMID 25031551, 2014). "High serum levels of TFF3 were significantly correlated with distant metastasis and an advanced stage in both types of cancer." (PMID 25031551, 2014).
cancer (continued). "Moderate or strong expression of TFF3 was predominantly localised in the cytoplasm of carcinoma cells with an infrequently positive signal located in stromal (fibroblast and endothelial) cells." (PMID 25266665, 2014). "All these genes (AREG, GREB1, TFF1 and TFF3) were up-regulated in ER+ carcinomas compared to ER- carcinomas (AREG was only borderline significant)." (PMID 21812955, 2011). "Additionally, we employed bulk RNA-seq, pan-cancer single-cell transcriptomics, ST, and proteomics to show that TFF3 is positively correlated with MAPK activation and EMT." (PMID 41551914, 2026). "TFF3 has been shown to facilitate malignant progression in various cancers." (PMID 41551914, 2026). "Trefoil factor 3 (TFF3) modulates cancer development through pathways like MAPK/ERK and PI3K/AKT." (PMID 40452847, 2025). "Given the reported functions of TFF3 in modulating RTK-mediated cellular functions, including the data herein, it may be thus reasoned that RTK inhibition in cancer will be rendered more efficacious by TFF3 depletion or inhibition." (PMID 39920140, 2025). "SPINK1 expression was predominantly observed in a subgroup of cancers that expressed TFF3 (6/6)." (PMID 38256434, 2024). "SPINK1 expression was predominantly observed in a subgroup of cancers that expressed TFF3." (PMID 38256434, 2024). "Since protein–protein interaction is essential in the molecular mechanisms underlying carcinogenesis and cancer progression and aggressiveness, aberrant FCGBP expression may regulate cancer behaviors by functional interactome linking with TFF3." (PMID 35626334, 2022). "Interestingly, TFF3 has multifaceted effects from a pre-neoplastic lesion to invasive cancer, and the roles in several cancer subtypes have been extensively discussed." (PMID 35626334, 2022). "Moreover, FCGBP correlates to TFF3, a prognostic biomarker in various cancers, at transcriptional and translational levels." (PMID 35626334, 2022). "In the future, TFF3 may be used as a molecular target of functional antagonism in combination with other chemotherapeutic drugs to slow down cancer progression." (PMID 35039476, 2022). "A serum pepsinogen I / pepsinogen II ratio of <3.0 has 85% sensitivity and 74% specificity for cancer, and a serum level of trefoil factor 3 (a protein secreted by the gastrointestinal tract) of 3.6 ng/mL or more had 81% sensitivity and 81% specificity for cancer." (PMID 34604249, 2021). "Since TFF3 has been demonstrated to promote cell motility, invasion, and proliferation in cancer cells and stimulate some signaling pathways, we wondered whether these functions are dependent on the interaction of TFF3 with CD147." (PMID 34262017, 2021). "Indeed, TFF3 acts as a promiscuous activator of multiple survival pathways in cancer cells, including HER1-4, PI3K/AKT, RAS/MEK/MAPK, and cSRC/STAT3, which are critically associated with enhanced cancer cell survival, metastasis, and resistance to therapy." (PMID 30451834, 2018). "Importantly, the propensity of cancer cells from TFF3-positive cancers to depend on TFF3-driven survival and dissemination represents a fundamental rationale for target-based therapeutic approaches against TFF348." (PMID 30451834, 2018). "However, a plethora of evidence substantiates a potent role of TFF3 in cancer progression (see Introduction)." (PMID 30451834, 2018). "However, elevated TFF3 expression is observed not only in HCC but also in other cancers and inflammatory conditions." (PMID 28445151, 2017). "The existence of epigenetic cancer field effects in relation to PC has previously been reported for a number of aberrantly hypermethylated genes, but further studies are needed to investigate if this is also the case for TFF3 promoter hypomethylation." (PMID 28930171, 2017). "In addition, overexpression of TFF3 decreased the sensitivity of cancer cells to chemotherapy by mediating Bcl-2." (PMID 28070169, 2017).
cancer (continued). "TFF3 also may contribute to cancer metastasis with epithelial-to-mesenchymal transition (EMT) potentially through the regulation of genes such as androgen receptor (AR), FOXA1 and human epidermal growth factor receptor-type 2 (HER2)." (PMID 28070169, 2017). "Furthermore, in our cohort of EC patients, TFF3 expression is positively associated with myometrial invasion, indicating that TFF3 likely promotes EMT leading to cancer progression." (PMID 29100386, 2017). "The effects of TFF1 and TFF3 for cancer progression is still controversial." (PMID 28687783, 2017). "The TFF3 gene, which plays a role in mucosal protection and repair in the gastrointestinal tract, is known to be induced by estrogen, and it is over-expressed in several types of cancer." (PMID 19402886, 2009). "Nevertheless, little is known about whether TFF3 directly contributes to the malignant behaviour of cancer cells." (PMID 18682706, 2008). "Importantly, overexpression of TFF3 has been reported to be prognostically important in several of these cancers." (PMID 18682706, 2008). "All eight definite carcinomas showed greatly decreased expression levels of TFF3 mRNA." (PMID 15083192, 2004). "However, the expression of TFF3 protein in cancer tissue was predominately located in PDAC cells." (PMID 35332126, 2022). "Additionally, FCGBP might interact with TFF3, an essential protein in the pathogenesis of several cancers." (PMID 35626334, 2022). "Cytosponge-TFF3 testing could also lead to the diagnosis of treatable dysplasia and early cancer." (PMID 32738955, 2020). "Hence, pharmacological inhibition of TFF3 in cancer, either as a monotherapy or in combination with standard of care therapies, may be considered." (PMID 31658702, 2019). "In addition, the cases with residual carcinoma that express TFF3 in resection specimens, they also show expression of TFF3 in pre-neoadjuvant biopsies, since the expression of TFF3 is similar in pre-neoadjuvant core needle biopsies and resection specimens with residual carcinoma." (PMID 30744593, 2019). "Therefore, we speculated that TFF3 exerts its protective effects on scattering cancer cells via regulatory ncRNAs." (PMID 28149533, 2017). "Additionally studies have demonstrated that the aberrant expression of TFF3 in vivo is correlated with inflammation of the gastrointestinal tract and a variety of solid tumors, including gastric cancer, breast cancer and other cancers." (PMID 24282531, 2013). "The specific roles and mechanisms of TFFs remain unclear; however, sufficient evidence from both clinical and experimental studies has indicated that TFF3 is involved in the pathological processes of several human diseases, such as mucosal disorders and cancer." (PMID 24282531, 2013). "In our pan-cancer analysis of 6 immune subtypes, we observed that the C2 subtype, characterized by the dominance of IFN-γ, was distinctly lower in high-TFF3-expression groups than in low-TFF3 groups." (PMID 41551914, 2026). "Elevated expression of TFF3 promoted the oncogenicity of ER+HER2+ MC cells, including enhanced cell proliferation, survival, anchorage-independent growth, 3D growth, cancer stem cell-like (CSC-like) phenotype, migration, invasion, and xenograft growth." (PMID 39920140, 2025). "Previous studies have reported that the pharmacological inhibition of TFF3 modulates the PI3K/AKT, MAPK, WNT, and JAK/STAT3 signaling pathways in carcinoma cells." (PMID 39920140, 2025). "In addition, TFF3 may influence the metastasis of cancer cells in epithelial tissues." (PMID 37569301, 2023). "Forced expression of TFF3 promoted oncogenic functions of PDAC cells in vitro including cell proliferation, survival, foci formation, cancer stem cell-like behavior and invasion, ex vivo colony growth in 3D-Matrigel, and xenograft growth in vivo." (PMID 35332126, 2022). "IHC analysis further revealed that depletion of TFF3 in SW1990 cells resulted in reduced proliferation and increased apoptosis of cancer cells." (PMID 35332126, 2022).